TNF (tumor necrosis factor)
Diseases named in the same sentence as TNF in open-access papers (continued):
Sharing a sentence is not in itself a finding about the gene and the disease.
tumor (continued). "Macrophages induce the generation of reactive oxygen species (ROS) within tumor cells through secretion of various stimuli, such as tumor necrosis factor alpha." (PMID 27047180, 2015). "A number of proinflammatory mediators are present in tumor microenvironments, among which TNFα is shown to promote tumor progression potentially by inducing MCP-1 production inside tumors." (PMID 26167165, 2015). "Comparatively, TNF-α led to less apoptosis of tumor cells (2.48 ± 0.36%) than mechanic stimulations (4.01 ± 0.65%), demonstrating the significant role of mechanical environment in influencing tumor cell viability." (PMID 26631692, 2015). "High levels of mSAA3 expression upon stimulation with cytokines, such as TNFα, derived from the primary tumor site can only be seen in lung endothelial or epithelial cells, along with myeloid derived immune cells." (PMID 25738827, 2015). "For instance, neutrophil delivered TNFα, IL-6, and IL-17 were shown to promote tumor growth by modifying the function of stromal cells surrounding the tumor." (PMID 26648665, 2015). "A novel discovery was the role of tumor cell NF-κB on post-treatment immune signaling by macrophages, which led to a substantially higher release of TNF-α and IL-6 by macrophages." (PMID 26307977, 2015). "As NF-κB signaling pathway is a major mediator of the tumor-promoting activities of TNF-α, we thus present the first report of the investigation of the role of silibinin in modulating TI-induced FAT10 expression and its functional consequences." (PMID 26142316, 2015). "These TANs were more cytotoxic toward tumor cells and produced higher levels of tumor necrosis factor-alpha (TNF-α), NO, and H2O2." (PMID 26819959, 2015). "In whole tumor tissue samples, we found higher TNF-α and CCL2 gene expression, along with higher CCL3 protein expression in cachectic patients, as compared to WSC." (PMID 26732354, 2015). "Tumour necrosis factor-α (TNF-α) is critical in the regulation of inflammation and tumour progression." (PMID 26165253, 2015). "Consistent with the previous report of PPARγ suppression of iNOS expression, we similarly observed that ligand-mediated, sumoylated PPARγ decreased the expression of COX2 and TNFα, and thus suppressed tumor cell migration and growth." (PMID 26244663, 2015). "Both NF-κB and STAT3 mediated signals derived from tumor cells or infiltrating immune cells such as IL-1β, TNF-α, ROS or TLRs play a key role in the inflammatory activation of stromal fibroblasts associated to pathologies such as RA and cancer." (PMID 26501341, 2015). "HuR is a RNA-binding protein that orchestrates the stabilization and translation of mRNAs, critical in inflammation and tumor progression, including tumor necrosis factor-alpha (TNF)." (PMID 26553968, 2015). "A prime example of such complementary targeting is TNFα targeted to tumors with the NRG tumor-homing peptide; such a conjugate is now in phase 3 clinical trials, and CAR-peptide targeted decorin." (PMID 26437400, 2015). "If on one side tumor cells secrete a plethora of factors such as TGF-β1, PDGF, VEGF, IL-6, FGF-2, IFN-γ, TNF, MMPs involved in fibroblast activation, on the other side CAFs produce the same molecules that in turn affect tumor aggressiveness." (PMID 25474039, 2015). "Differences were observed in tumours treated with either CDDP or electrochemotherapy in comparison to tumours treated with TNF-α in combination with CDDP or electrochemotherapy." (PMID 25810699, 2015). "This stage of tumour development has been modelled in Drosophila by expression of active Ras, which can be used to generate tumours that depend on TNFα for invasive outgrowth." (PMID 25948885, 2015). "Smad7 overexpressing T cells further exhibited direct killing of tumor cells via TNF-α, thus demonstrating an additional mechanism accounting for Th17/Th1 hybrid cell antitumor functions." (PMID 26583099, 2015).
tumor (continued). "There was a high release of TNFα both in human macrophages and mouse tumor tissues with Sal-YB1 treatment." (PMID 26286454, 2015). "TNF-α, a major mediator of inflammation, is a tumor promoter factor contributing to stromal development, inflammation, and tumor spread, particularly when chronically produced." (PMID 26158775, 2015). "A similar effect was found using PDT, in which inhibition of NF-κB with Bay 11-7082 in human glioblastoma cells augmented TNF-α-induced tumor cell death following PDT." (PMID 26516076, 2015). "We then intravenously injected the TNF-α preparations into non-tumor-bearing healthy BALB/c mice and collected blood samples at various time points." (PMID 26678960, 2015). "On one hand, activated neutrophils are capable of killing tumor cells through oxidative bursts and secretion of anti-tumor cytokines such as TNF-α and IFNs." (PMID 25828472, 2015). "NF-κB association with the NOS2 promoter chromatin was detected in three regions of the NOS2 promoter region in TNFα-treated tumor cells." (PMID 26497740, 2015). "In the presence of TNF-α, although the viability of the tumor cells was compromised, most of them were still alive (more than 90%)." (PMID 26631692, 2015). "Recent studies have demonstrated the importance of tumor necrosis factor-α (TNF-α) in promoting tumor growth and in the progression of ovarian malignancies." (PMID 25624918, 2015). "As assessed by a real-time PCR assay, the concentration of TNF-α mRNA increased significantly in HFs upon co-culturing, whereas its mRNA concentration in tumor cells remained low and constant." (PMID 26418748, 2015). "Mice bearing large tumors were used because they are more sensitive to TNF-α induced toxicity than non-tumor-bearing mice (ref here)." (PMID 26678960, 2015). "We also studied simulating more complex conditions on the chip by simultaneously exerting both mechanical (FSS and CS) and biochemical (TNF-α) stimulations on the tumor cells-ECs interaction." (PMID 26631692, 2015). "Pro-inflammatory molecules such as IL-1β, IL-6 and PGE2 are thought to promote the induction of MDSC in tumours, whereas pro-inflammatory TNF signalling can drive the accumulation of MDSC in tumours." (PMID 25738302, 2015). "It has become increasingly clear that inflammatory cytokines such as TNFα facilitate both tumor development and metastatic progression." (PMID 25762639, 2015). "The aim of this study was to investigate the relationship of pretreatment serum IL-6 and TNF-α levels on tumour recurrence in patients with OSCC in order to identify potential biomarkers for the early detection of disease recurrence." (PMID 25858079, 2015). "Similar to naïve mice, tumor-bearing animals, which received the CpG or CpG-siRNA constructs elaborated higher serum levels of IL-6, TNF-α, IFN-γ and IL-12p70 compared to PBS-treated controls." (PMID 26327508, 2015). "The number of the adhered tumor cells on the ECs monolayer decreased in the presence of TNF-α compared with the control (P < 0.05, Two-Sample t-test)." (PMID 26631692, 2015). "Proinflammatory cytokines, such as tumor necrosis factor alpha (TNFα) and interleukin-6 (IL-6), lead to an inflammatory state that stimulates tumor growth." (PMID 26347776, 2015). "Serum levels of TNFα are significantly increased in RCC patients as well as secretion by tumor cells and it was demonstrated that TNFα promotes EMT in RCC by decreasing E-cadherin expression and increasing vimentin expression and MMP9 activity." (PMID 26579493, 2015). "For example the secretion of the antitumor cytokines IFN-γ and TNF-α by activated Th1 and NK cells is a feature of effective tumor vaccines." (PMID 26305550, 2015). "Tumor necrosis factor-α (TNF-α) is one of the major pro-inflammatory cytokines and paradoxically can be either a tumor promoter linking inflammation with carcinogenesis or a tumor inhibitor as it induces cancer cell death due to the sustained JNK activation." (PMID 25419573, 2014).
tumor (continued). "Several in vitro and animal experiments using OSCC cells have shown that tumor cells produce several cytokines, including interleukin-6 (IL-6), IL-11, TNFα and parathyroid hormone-related protein (PTHrP)." (PMID 25373602, 2014). "Of note however, γδ17 constituted approximately 25% of all tumor-infiltrating Vδ1 cells and co-produced TNF-α, IL-8, and GM-CSF." (PMID 25505472, 2014). "Systemic administration of CGA (1 μg) to lymphoma-bearing mice potently reduces the TNF-elicited penetration of a synthetic dye (patent blue) in tumor tissues, confirming previous observations that CGA can affect host/tumor interactions." (PMID 25177680, 2014). "Hepatic IR treatment significantly promoted CT26 tumor growth in the liver, but either Enbrel or low-dose TNF-α pretreatment reversed this trend." (PMID 24397824, 2014). "Deregulated TNF expression within the tumor microenvironment seems to favor malignant cell tissue invasion, migration, and final metastatic formation." (PMID 25197311, 2014). "Both proteins, IL-1α and -β, have been implicated in tumor progression by inducing the expression of angiogenic and metastatic genes, cytokines and growth factors, such as MMPs, VEGF, IL-6 and 8, CCl2, CCL7, TNFα and TGFβ." (PMID 24887580, 2014). "Effector Th1 type helper CD4+ T cells with the ability to secrete IFN-γ and TNF-α can act as regulators in anti-tumour immunity and provide ‘help’ for the development of potent anti-tumour CTLs by supporting their expansion and memory development." (PMID 24520352, 2014). "In contrast, in hemocytes where TNF is also active, the downstream expression of metalloproteinases promotes tumor progression." (PMID 25071815, 2014). "Haptenation will also cause keratinocytes to release IL-1β, IL-6, IL-18, and TNFα, which have been shown to cause MDSC recruitment and infiltration at the tumor site, subsequently causing IL-10 release and immune suppression." (PMID 24949488, 2014). "TNF-alpha levels in tumour and liver tissue were increased, whereas VEGF levels in tumours and livers were reduced after pK1-5 treatment." (PMID 24895598, 2014). "Previous studies have found that several genes, including interleukin 6 and tumor necrosis factor-alpha, have opposite functions in normal and tumor cells." (PMID 24886599, 2014). "According to these findings, the pro- or antitumoral TNF-α response within the tumor microenvironment depends not only on local concentration but also on its expression site in the tumor." (PMID 24901008, 2014). "A high dose of TNF-α and IL-1β was found to induce tumor cell cytotoxicity and reduce tumor cell resistance to the apoptotic agent H2O2, in a synergistic manner." (PMID 25120672, 2014). "Larger TNF concentration (F) and larger tumor volume are accompanied by an increase in necrotic mass (N)." (PMID 24664144, 2014). "These authors suggested that B cells are required for optimal CD4+ and CD8+ T cell tumor immunity, noting that effector-memory and IFNγ– or TNFα–secreting CD4+ and CD8+ T cell induction was significantly impaired in B cell-depleted mice with tumors." (PMID 24498358, 2014). "M1 macrophages also contribute to tumor development by TNF-α and IL-6 signaling, enhancing carcinogenesis by increasing cell proliferation and neoangiogenic cell properties." (PMID 24829560, 2014). "Giving different dosage of P2 toward HeLa cells, we also observed its modulation of the inflammatory response in tumor cells, controlling the release of interleukin-6 (IL-6) and tumor necrosis factor-alpha (TNF-α)." (PMID 24683359, 2014). "Along the same line, some tumor cytokines, including Interleukin-1 beta, tumor necrosis factor-alpha and interleukin-6, were found to be elevated in HCC patients, have been reported to block IGF-1 production in the liver." (PMID 24586785, 2014).
tumor (continued). "DCs, which were induced from peripheral blood mononuclear cells (PBMCs) using granulocyte macrophage colony-stimulating factor (GM-CSF), IL-4, and tumor necrosis factor (TNF)-α, were then incubated with the α-Gal-expressing tumor cell lysate." (PMID 24741629, 2014). "The results obtained thus far in this study indicate that the cooperative activities of TNFα with RasG12V or with WT-Ras lead to additive elevation in the release of CXCL8 by the tumor cells." (PMID 24598028, 2014). "Tumour associated macrophages or myeloid-derived suppressive cells, CD4+ Foxp3+ Treg cells and Th17 cells and their associated cytokines Il-6, TNF, IL-1β, IL-23 and TGF-β are generally recognized as dominant tumour-promoting forces." (PMID 24963981, 2014). "Upon binding to EGF and tumor necrosis factor alpha (TNF-α), signaling pathways are activated with important downstream effects on tumor growth, mobility, survival and therapeutic resistance 78,79." (PMID 24702466, 2014). "We observed that TQ in combination with bortezomib produced significant reduction in the serum levels of TNF-α, which can contribute to the anti-tumor activity." (PMID 24504138, 2014). "A TNF-α tumor promotion mechanism is based on reactive oxygen species (ROS) and reactive nitrogen species (RNS) generation, which can induce DNA damage, hence facilitating tumorigenesis." (PMID 24901008, 2014). "Secondly, circulating neutrophils contributes to tumor growth and progression by producing cytokines, such as tumor necrosis factor (TNF), IL-1, IL-6, and angiogenic factor vascular endothelial growth factor (VEGF)." (PMID 25401500, 2014). "The groups treated with TNFα/MAGE-AX or GK-1 BMDCs remained similar in size throughout the treatment, whereas untreated mice and those inoculated with TNFα BMDCs showed an increased tumor growth rate compared to the other groups." (PMID 25759825, 2014). "Loading reovirus into LAKDC cocultures also increased production of the immunostimulatory cytokines, IFNɣ, TNFα, IFNα and IL-12p70, potentially reversing the suppressive nature of the tumor milieu to support generation of effective T cell responses." (PMID 23982804, 2014). "In human ovarian carcinomas, CXCL12-recruited pDCs have been shown to produce TNFα and IL-8, favoring tumor angiogenesis." (PMID 25072019, 2014). "Significant (P < 0.01) decreases of the splenic TNF-α, IL-1β and IL-10 contents were observed in tumor-bearing control mice as compared with intact control mice, respectively." (PMID 25477992, 2014). "Tumor Necrosis Factor (TNF)-α stimulates DC maturation, being used for induction of anti-tumor immunity, and promotes DC differentiation from monocytes." (PMID 24614867, 2014). "Fully calibrated, the model can simulate the response of tumors to TNF injections and will help predict optimal TNF treatment schedules to completely eradicate viable tumor cells." (PMID 24664144, 2014). "Our data showed that adoptive transfer of STZ-diabetic CD8+ effector cells resulted in fewer tumor-infiltrating T cells as well as less production of perforin, Granzyme B and TNFα in situ." (PMID 25390652, 2014). "TNF-α, a proinflammatory cytokine produced by both tumor and adipose tissue regulates adipocyte differentiation." (PMID 25415607, 2014). "In the present study, upon contact with tumor cells, macrophages were found to express a higher level of VEGF-C which was associated with an increase in the expression of IL-1β and TNF-α and their receptors." (PMID 25120672, 2014). "Dumont and colleagues have demonstrated that the supernatant from M1 polarized macrophages, which produce TNF-α, IL-1β and ROS, can induce tumor cell growth inhibition in vitro, and in gal-3 knockdown cells, it can increase cell death susceptibility." (PMID 25369297, 2014). "So far, TNF-α seem powerful to destroy tumor, but has fallen short of expectations in clinical use as an anti-tumor agent because of its indeterminacy at therapeutic doses." (PMID 24885472, 2014).
tumor (continued). "In studies on animal thoracic neoplasms, dermatoma and gastrointestinal cancer, the association between tumor cell growth and metastasis and the amount of TNF-α in the tumor microenvironment has been demonstrated." (PMID 24676340, 2014). "Metastatic tumor cells entering the liver trigger a proinflammatory response involving Kupffer cell-mediated release of TNF-α and the up-regulation of E-selectin in vascular endothelial cells." (PMID 25255877, 2014). "Efficacious anti-tumor therapeutic or vaccine approaches tested in murine models resulting in protection from tumors are characterized by strong Th1 polarization, M1 macrophage activation, a TNFα response, and an anti-tumor IFNγ-producing CD8+ CTL." (PMID 25072019, 2014). "The molecular mechanisms of TNF-α in tumor progression are due to its ability to activate multiple signaling pathways, including NFκB, that play critical roles in mediating cell proliferation and survival." (PMID 24682076, 2014). "In obesity and DM, tremendous amount of the tumor-promoting cytokines IL-6 and TNF-α are produced, which is thought to promote HCC development." (PMID 24918094, 2014). "As a consequence, TLR8 is activated and the immune cells release interleukin-6 (IL-6) and tumor necrosis factor alpha (TNF-alpha), which increase tumor growth and metastatic potential." (PMID 25356314, 2014). "Our findings showed that compared to the CT26 group, the CT26 + IR group showed significantly increased tumor load whereas the CT26 + IR + Enbrel and CT26 + IR + TNF-α groups showed markedly reduced tumor loads." (PMID 24397824, 2014). "The TNF pathway plays a dual role during tumor control: cells adjacent to tumor clones activate TNF-signaling to drive tumor cells into apoptosis thus limiting tumor growth." (PMID 25071815, 2014). "On the other hand, both IGF-1 and TNF-α are involved in the formation of reactive tumor microenvironment." (PMID 25203554, 2014). "Classical xenograft studies in nude mice showed that BCG suppressed the TNF-α action of tumor clearance; rather promoted tumor formation." (PMID 25208737, 2014). "Gelatinase B/MMP-9 is considered to be a tuner and amplifier of inflammatory and immune functions and is up regulated by pro-inflammatory cytokines such as TNFα, IL-1β, IL-6 and TGFβ in a wide variety of human tumour cells, stromal and endothelial cells." (PMID 24473089, 2014). "In this context, high concentrations of TNF-α were shown to induce hyperpermeability and structural disruption in tumor vasculature, thus promoting tumor necrosis and enhancing the efficacy of traditional cytostatic drugs." (PMID 24672527, 2014). "Tumor neovascularization or angiogenesis is closely related with proangiogenic factors such as VEGF, IL-8, IL-6, TGF and TNF released by tumor cells and immune cells." (PMID 24555849, 2014). "Co-culture of human eosinophils and their conditioned media with the colon carcinoma cell line Colo-205 led to the production of TNF, which was involved in tumor cell killing along with granzyme A." (PMID 25426119, 2014). "In the subgroup analysis by tumour–node–metastasis stages, the highest TNF-α level was found in stage IV (42.7 ± 12.5 pg/mL) and was significantly elevated compared to earlier stages of CRC and controls." (PMID 26019577, 2014). "Based on all of these results, we found a tumor promoter gene in H. pylori genome that induces TNF-α gene expression." (PMID 24469254, 2014). "Recent reports have shown that TNFα can promote influx of tumor-reactive T cells by remodeling intra-tumor vessels, and thereby exerts a local immunomodulatory function in tumor microenvironment." (PMID 25390652, 2014). "Experimental transfection of a transformed BALB/3T3 cell line with H. pylori genes revealed that tumor progression was dependent on Tipα-induced production of TNF-α." (PMID 24672527, 2014).